CPT1A (carnitine palmitoyltransferase 1A)
Diseases named in the same sentence as CPT1A in open-access papers (continued):
Sharing a sentence is not in itself a finding about the gene and the disease.
infection (15 papers, 2012 to 2025). The state of being infected such as from the introduction of a foreign agent such as serum, vaccine, antigenic substance or organism. "Carnitine palmitoyltransferase 1a (Cpt1a) is considered the rate-limiting enzyme for mitochondrial metabolism of long-chain fatty acids, and Cpt1a deficiency is associated with infant mortality and infection risk." (PMID 36513703, 2022). "The current work was undertaken to further this observation by determining if a common human Cpt1a variant is associated with infection risk and to define the mechanisms underlying the link between Cpt1a insufficiency and increased susceptibility to infection." (PMID 36513703, 2022). "Further studies to determine if the CPT1A p.P479L variant impacts immune response to infection are needed, information that will be important for the development of culturally relevant public health strategies in reducing childhood morbidity and mortality." (PMID 34295859, 2021). "In addition, CPT1A inhibition is associated with a higher risk of infection and impairment of neutrophil response." (PMID 37600769, 2023). "This infection susceptibility is associated with impaired neutrophilic responses to infection in mice and humans, and mechanistic studies provide evidence that neutrophil chemotaxis and trafficking to the site of infection require Cpt1a-dependent mitochondrial fatty acid oxidation." (PMID 36513703, 2022). "This study provides a mechanistic framework that connects the clinical association between Cpt1a deficiency and increased infection risk to the previously unrecognized requirement of Cpt1a-dependent FAO for neutrophil chemotaxis and trafficking that is required for optimal host defense." (PMID 36513703, 2022). "This study was undertaken to test the hypothesis that impairment in Cpt1a-dependent fatty acid oxidation results in increased susceptibility to infection." (PMID 36513703, 2022). "Children homozygous for the CPT1A p.P479L variant may experience a more severe illness due to impaired ketogenesis or impaired response of the immune system during infection." (PMID 34295859, 2021). "Given the dependence of immune cell function on metabolic programs and the genetic link between reduced Cpt1a function and infection risk, the current work was undertaken to determine if impairment in Cpt1a-dependent fatty acid oxidation results in increased susceptibility to infection." (PMID 36513703, 2022). "Targeting carnitine palmitoyl transferase 1a (Cpt1a), a key enzyme in fatty acid metabolism, impaired neutrophil migration to infection sites and enhanced their antimicrobial activity." (PMID 39365825, 2024). "Targeting carnitine palmitoyl transferase 1a (Cpt1a)-a crucial enzyme in mitochondrial β-oxidation-either through chemical or genetic methods impairs neutrophils’ ability to migrate to infection sites while also enhancing their antimicrobial function." (PMID 39365825, 2024). "Together, these findings demonstrate an association between a genetic defect in Cpt1a-dependent FAO and an increased risk of infection in humans." (PMID 36513703, 2022). "The infection successfully removed the loxP-flanked region containing the CPT1A exon 4, since gDNA amplicon from both sides of the homologous region dropped to 219 bp compared to control (GFP) cells 1030-bp amplicon." (PMID 29396649, 2018). "The amplicon from exon 3 to 5 from CRE-infected cDNA with an expected 116-bp length was barely detectable after 24- and 48-h infections, which indicates great instability of the deleted CPT1A mRNA product." (PMID 29396649, 2018). "CPT1A genotypes were available for 35 of the 81 unexpected infant deaths (SIDS/SUDI or infection) during the review period." (PMID 23231747, 2012). "An association with infection susceptibility has not been established for FAODs other than Cpt1a deficiency." (PMID 36513703, 2022).
infection (continued). "Classic CPT1A deficiency (OMIM:255120) is a rare autosomal recessive disease presenting during infancy as hypoketotic hypoglycemia and metabolic decompensation triggered by prolonged fasting and/or vomiting, often precipitated by active infection." (PMID 34295859, 2021). "However, studies are required to fully resolve whether the metabolic reprogramming associated with NK cell activation is essential to NK cell immunity, and to elucidate the roles of NK cell-specific NRF1 and CPT1a in host immunity against infection." (PMID 38426112, 2024). "On the other hand, we uncovered that the relative abundance of CPT1A and CPT2, which encode Carnitine O-palmitoyltransferase, a rate-limiting enzyme involved in the fatty acid oxidation (FAO), were significantly up-regulated post infection, indicating accelerated FAO pathway." (PMID 37256871, 2023). "CPT1A P479L homozygosity, which has been previously associated with infant mortality in Alaska Native and British Columbia First Nations populations, was associated with unexpected infant death (SIDS/SUDI, infection) throughout Nunavut (OR:3.43, 95% CI:1.30-11.47)." (PMID 23231747, 2012). "By promoting mitochondrial biogenesis and the expression of carnitine palmitoyl transferase 1A (CPT1A), which regulates FAO, IL-15 controls the bioenergetic stability of memory T cells after infection." (PMID 36359329, 2022). "Within a week after infection of SKOV-3, OVCA-432 and OVCAR-3 with CPT1A shRNA lentivirus, subpopulations of cells showed morphological appearances of senescence." (PMID 26716645, 2016). "Although most individual genes were not statistically significant, Cpt1a showed around 2-fold induction, which was significant 6 h post infection." (PMID 35013270, 2022). "Flow cytometry analysis of lungs collected 10 days post-infection confirmed accumulation of progenitors at the expense of differentiated SAEC in animals carrying the deletion of Cpt1a in the non-hematopoietic compartment, independently of the genetic status of the donor-derived immune cells." (PMID 36781848, 2023). "Due to the use of a systemic pharmacologic inhibitor of Cpt1a in the mouse models, infection-related outcomes cannot be specifically attributed to impaired neutrophil trafficking as it is likely that the effects of Cpt1a inhibition in non-neutrophils impact the course of infection." (PMID 36513703, 2022). "In this sense, it was surprising to observe a marked reduction of CPT1A levels in VACV-infected BMDMs despite the increased gene expression, which suggests that FAO is not enhanced during infection of BMDMs." (PMID 36453897, 2022).
kidney disease (6 papers, 2021 to 2025). "The assessment of the renal metabolome in CKD and expected FAO-GOF by CPT1A OE may provide valuable information in understanding the complex interaction between metabolism and kidney disease." (PMID 37377862, 2023). "Whereas the role of tubular CPT1A (which encodes a protein located at the outer mitochondrial membrane) in cellular and molecular changes associated with kidney fibrosis has been elucidated, the role of CPT2, which is located in the inner membrane, in kidney diseases remains unclear." (PMID 35998043, 2022).
adenocarcinoma (2 papers, 2020 to 2024). A common cancer characterized by the presence of malignant glandular cells. "Muscle lipid stores were also decreased in Colon-26 adenocarcinoma mouse muscle samples, and expression of the beta-oxidation gene CPT1A was negatively associated with muscle quality in cachectic patients." (PMID 38429578, 2024). "Conversely, one sample with adenocarcinoma features showed less CPT1A associated with less SHMT2, MTHFD2, and PSAT1 expression." (PMID 33218188, 2020). "Particularly, we searched for studies that compared adenocarcinoma with aggressive disease like small cell NEPC and focused on serine and one carbon metabolism, CPT1A and AR expression in clinical data." (PMID 33218188, 2020).
central nervous system diseases (2 papers, 2022 to 2023). "Dysregulation of metabolic pathways by carnitine palmitoyl-transferase 1 ‘CPT1A’ plays a key role in central nervous system disorders." (PMID 35627112, 2022). "However, we have previously observed similar effects with CPT1 and CPT1A inhibition considering inflammatory- and oxidative stress levels in other animal models mimicking central nervous system diseases using female rodents." (PMID 36681683, 2023).
hematologic malignancies (2 papers, 2021). "Previous reports demonstrated that CPT1a acts as a potential molecular target in solid tumors and hematologic disease." (PMID 33926484, 2021). "CPT1A inhibitors, such as etomoxir and ST1326, are effective against hematologic malignancies, and in our hands, nearby adipocytes actually enhanced the cytotoxicity of etomoxir against ALL." (PMID 33968771, 2021).
kidney (2 papers, 2022 to 2023). "Consistent with the determined mechanism, we observed that CPT1a and KAT2a proteins were highly co-expressed within lung and liver metastases compared to cranial bone and lymph node metastases." (PMID 36732635, 2023).
head and neck tumors (1 paper, 2022). "High expression of CPT1A in head and neck tumors is associated with reduced overall survival of patients." (PMID 35411000, 2022). "In the TCGA dataset, 42 cases out of 279 head and neck tumors showed CPT1A gene amplification." (PMID 35411000, 2022).
CPT1A also shares sentences with these, for which no sentence is quoted: cardiovascular disease (3 papers); fibrosis (3); Hyperinsulinemia (3); amyotrophic lateral sclerosis (2); bacterial infection (2); Dyslipidaemia (2); endotoxemia (2); fatty acid metabolism disorder (2); non-small cell lung carcinoma (2); Parkinson disease (2); schizophrenia (2); systemic lupus erythematosus (2); alveolar rhabdomyosarcoma (1); anorexia nervosa (1); aristolochic acid nephropathy (1); arterial disease (1); atopic dermatitis (1); attention-deficit and hyperactivity disorder (1); autosomal inherited recessive disorders (1); benign breast disease (1); bone metastasis (1); brain tumors (1); Cachexia (1); Carnitine palmitoyltransferase 1 deficiency (1); cystic kidneys (1); dementia (1); dermatitis (1); diabetic cardiomyopathy (1); endometrial cancer (1); epilepsy (1).
A further 48 diseases each share a sentence with CPT1A in 1 paper.